EPCAM (epithelial cell adhesion molecule)
Diseases named in the same sentence as EPCAM in open-access papers (continued):
Sharing a sentence is not in itself a finding about the gene and the disease.
tumor (continued). "Antibody staining confirmed that the samples displayed a wide range of immune infiltrate levels (CD45+ cells), endothelial cells (CD31+) and cancer cell markers (CA IX, CD10, and EpCam), indicating variability in tumor cell profiles within the collected samples." (PMID 40589567, 2025). "However, due to the heterogeneity among tumor cells, some cells inherently express low levels or lack expression of EpCAM." (PMID 39743435, 2025). "Oportuzumab Monatox-qqrs or Vicineum is a recombinant fusion protein designed to block protein synthesis and mediate tumor cell death by selectively targeting epithelial cell adhesion molecule (EpCAM)-expressing cells, which are commonly found in various solid tumors." (PMID 40002231, 2025). "The IsoFlux system (Fluxion Biosciences, Inc., Alameda, CA, USA) is a semi-automated platform that enriches circulating tumor cells (CTCs) by combining EpCAM-based immunomagnetic positive selection with microfluidic technology, similar to the FDA-approved CellSearch system." (PMID 40076201, 2025). "Similar to size‐based separation, EpCAM+ cell isolation enriched tumor cells by only an average of 2.5‐fold, and the recovery rate was low as well, averaging 14.5%, implying that a significant number of the initial EpCAM+ cells were lost during the procedure." (PMID 40525275, 2025). "These patterns may reflect the distinct biological roles of these markers, with CEA and EpCAM integral to cell adhesion and epithelial integrity, accounting for their residual expression in normal tissues and the tumor bed post-nCRT." (PMID 40563608, 2025). "The moderate correlation (rspearman>0.66) between ASGPR protein and EpCAM mRNA, GPC‐3 mRNA, and EpCAM protein implies that combining these biomarkers could provide a more comprehensive view of tumor progression, potentially improving HCC diagnostic efficacy." (PMID 39556692, 2025). "In conclusion, patient-derived organoids were successfully established from PARPi-resistant HGSOC cell lines, retaining the original tumor architecture and biomarker expression (EpCAM, CA125, PAX8, HER2, MEK1/2, Cyclin E1), thus validating their use as preclinical models." (PMID 41009433, 2025). "Tumor cells are positively selected by anti-epithelial cell adhesion molecule (EpCAM)." (PMID 40831937, 2025). "Since EpCAM is a sensitive and specific tumor marker in the context of MPEs, we next employed immunomagnetic‐based cell isolation as an alternative enrichment method, utilizing anti‐EpCAM antibody‐coated magnetic beads to capture and isolate tumor cells from MPEs." (PMID 40525275, 2025). "Notably, more than 50% of the tumor cells were recovered following depletion, a rate that is significantly higher than that obtained by EpCAM‐positive selection and size‐based enrichment strategies." (PMID 40525275, 2025). "In addition, we observed a similar pattern of lysis in two primary (patient) tumor cell samples with EpCAM IgA mAb (with CD47 blockade)." (PMID 40358156, 2025). "In this study, we applied a multiplex TMA strategy to profile the expression landscape of EGFR, EpCAM, TF, and TROP2 in TNBC specimens and explored associations between their expression and clinicopathological features, including tumor grade, tumor stage, HER2 status, and Ki-67 expression." (PMID 40806559, 2025). "Additionally, a specific resistant tumor cell phenotype (EpCAM+ CD45+) has been detected in the ascites of individuals diagnosed with EOC." (PMID 40757000, 2025). "Epithelial cell adhesion molecule (EpCAM) was used to identify tumor cells in BC samples." (PMID 40148963, 2025). "Notably, EpCAM-ReTARGTPRIFNαR149A significantly enhanced the cytotoxic capacity of PBMCs of donor #4, whereas EpCAM-ReTARGTPRvIL2 only marginally enhanced tumor cell lysis even at the highest PBMC:OvCAR3 (5:1) cell ratio." (PMID 40243928, 2025).
tumor (continued). "Since there were some reported EpCAM CARs in other tumor models, we constructed a reported EpCAM CAR composed of a fully human scFv derived from a reported anti-EpCAM monoclonal antibody named UBS54 with a Y6F mutation and evaluated its anti-tumor efficacy together with our EpCAM CAR." (PMID 41417221, 2025). "Thus, we utilized flow cytometric analysis, using antibodies targeting EpCAM (tumor cells) and CD45 (pan‐leukocyte marker) to distinguish between tumor cells and immune cells within MPE samples." (PMID 40525275, 2025). "Notably, the Pt#3 tumor, despite having high EpCAM expression and high αSMA expression compared to samples Pt#2, Pt#8 and Pt#10, exhibited partial treatment response." (PMID 41315187, 2025). "The observed coexistence of both molecular subtypes and heterogeneity, which we have also observed for EpCAM and Vimentin, might explain the observed minor variations between tumor tissue and tumor organoids." (PMID 40296444, 2025). "The EpCAM positivity of patient sample #14 was 70% after tumor cell purification." (PMID 40358156, 2025). "KRT19, an intermediate filament protein, contributes to cytoskeletal organization and epithelial integrity in luminal subtypes (e.g., MCF7 and T47D) and is associated with cell adhesion and tumor progression via interactions with KRT8, KRT18, and EPCAM, as suggested by STRING analysis." (PMID 40806403, 2025). "Biochemical methods primarily employ antigen-antibody interactions by applying specific antibodies to tumour-specific biomarkers such as epithelial-cell adhesion molecule (EpCAM), prostate-specific antigen (PSA) and human epidermal growth factor receptor 2 (HER2)." (PMID 40343687, 2025). "Notably, EpCAM demonstrates elevated expression in cancer stem cells and circulating tumor cells, where it plays a pivotal role in tumor recurrence and metastatic dissemination." (PMID 41417221, 2025). "We also evaluated the expression of EpCAM in established tumours of TUBO and 4T1." (PMID 40792441, 2025). "In T_EP, there was significant upregulation of genes associated with malignancy, such as EPCAM, HSPB1, CEACAM6, MUC1, and LY6E, implicating their roles in tumor initiation." (PMID 40786043, 2025). "Thus, the main aim of this study was to evaluate how the modification of radiometal-chelate complex would influence the biodistribution and tumor-targeting properties of Ec1 labelled with gallium-68 for visualizing the EpCAM expression." (PMID 40445498, 2025). "Tumor organoids of patient R24, while displaying a basal‐like profile at baseline, showed a diverging marker expression after exposure to any of the tested chemotherapies, with EpCAM expressed in up to 100% of treated and analyzed tumor organoids." (PMID 40296444, 2025). "Microfluidic devices with multiple antigen binding capacity have also been developed for rapid enrichment of EVs from the blood, and often include epithelial cell adhesion molecule (EpCAM) along with various other surface proteins shown to be upregulated in different tumours." (PMID 40552103, 2025). "We evaluated the performance of eight different commercial streptavidin magnetic beads to capture cell line-derived tumor cells in blood labeled with EpCAM biotin monoclonal antibodies on our previously developed Flow-through Immunomagnetic CTC Enrichment system using 1 mL blood aliquots." (PMID 40343949, 2025). "Hence, utilizing EpCAM magnetic beads for positive selection also proved inefficient for tumor cell enrichment from MPEs." (PMID 40525275, 2025). "We found that folate receptor 1 (FOLR1), a known secretory protein, was upregulated in tumor tissues and positively associated with 3 major stem/progenitor markers, KRT19, EPCAM, and PROM1, and a poor prognosis for HCC patients in both the discovery and validation cohorts." (PMID 40038575, 2025).
tumor (continued). "Histopathological and immunohistochemical analyses confirmed that these organoids recapitulated the architectural and molecular features of the original tumors, including expression of established tumor markers (EpCAM, CA125, PAX8) and potential therapeutic targets (HER2, MEK1/2, Cyclin E1)." (PMID 41009433, 2025). "Under a uniform bias field, the SMS generates controllable magnetic gradients within the microchannel, producing distinct lateral velocities among EpCAM-labeled tumor cells that carry different Dynabead loads, which indirectly report membrane protein expression." (PMID 41597791, 2025). "At the REL stage, the majority of cancer cells reverted to an EpCAM+ epithelial phenotype following both protocols, suggesting that a substantial subset of the few surviving tumor cells in immunocompetent hosts had undergone a transient loss of epithelial characteristics." (PMID 40738896, 2025). "DARPins binding to such tumor-associated molecular targets, such as human epidermal growth factor receptor 2 (HER2), epithelial cell adhesion molecule (EpCAM), epidermal growth factor receptor (EGFR), vascular endothelial growth factor (VEGF), and hepatocyte growth factor (HGF) have been described." (PMID 40508045, 2025). "Epithelial cell adhesion molecule (EpCAM), a transmembrane glycoprotein, plays an essential role in the regulation of intramembrane proteolysis-mediated signaling and activation of Wnt signaling, promoting tumor cell growth and migration." (PMID 40565299, 2025). "HCC was the only tumor among the seven studied that rarely metastasized to lymph nodes, a finding that may reflect differences in EPCAM expression among cancers." (PMID 41228323, 2025). "Integrating AI technologies for precise detection and monitoring of EpCAM expression, coupled with a deeper understanding of EpCAM’s role in tumor biology, could pave the way for more effective and safer therapeutic approaches." (PMID 39996844, 2025). "In vitro assays revealed that M701 specifically trafficked CD3-positive cells to EpCAM-positive cells and caused lysis of only tumor cells with moderate-to-high EpCAM expression, indicating that M701 has few side effects on normal tissue." (PMID 41275209, 2025). "Overexpression of EpCAM and β-catenin in Dt81 hepa cells increases tumor formation." (PMID 40791212, 2025). "DARPins binding to tumor-associated molecular targets such as human epidermal growth factor receptor 2 (HER2), epithelial cell adhesion molecule (EpCAM), epidermal growth factor receptor (EGFR), vascular endothelial growth factor (VEGF) and hepatocyte growth factor (HGF) have been described." (PMID 40445498, 2025). "Combining EpCAM with cell-surface vimentin (CSV) in circulating tumor cell enrichment could also be a promising strategy to enhance the capture of heterogeneous CTC populations, while addressing the limitations of relying solely on EpCAM-based methods." (PMID 40076201, 2025). "Moreover, differences in cluster counts between surface markers (CD81, EpCAM, PD-L1) and the intravesicular marker Cyclin D1 also correlated with tumor stage." (PMID 41008614, 2025). "Indeed, a significant increase in EpCAM+ tumor cell percentage was observed after three rounds of depletion." (PMID 40525275, 2025). "The expression of the EpCAM molecule was only observed in tumor cell lines." (PMID 40869109, 2025). "In CRC, EpCAM is reported that overexpressed in more than 90% of tumor cells." (PMID 40236691, 2025). "EpCAM is a tumor cell exosome marker that differentiates between normal and tumor exosomes." (PMID 39911266, 2025). "Tumor regression quickly appeared 2 weeks after delivery of EpCAM CAR-T cells intravenously." (PMID 41417221, 2025). "Notably, co-cultures increased the size of the HTR2B + CRC cell population within the EpCAM+ (EpCAMlow and EpCAMhigh) tumor cells, too." (PMID 41034989, 2025). "EpCAM(+) CTCs decreased in tumor responders, and DCP increased in progressive cases." (PMID 40940925, 2025).
tumor (continued). "specifically linked high CD133 expression to reduced post-TACE OS, tumor multiplicity, vascular invasion, and cirrhosis, whereas EpCAM overexpression—while associated with age, tumor burden, and viral status—showed no OS correlation." (PMID 41438763, 2025). "Additionally, other EMT+ cells, circulating tumor stem cells (CTSCs), downregulate epithelial markers such as EpCAM while upregulating mesenchymal markers, and epithelial tumor cells, EMT+ tumor cells, and CTSCs coexist simultaneously in peripheral blood." (PMID 39996844, 2025). "Tumor cells are heterogeneous and have different EpCAM expression levels." (PMID 40343949, 2025). "Hence, we developed a co-culture assay to assess the anti-tumor activity of EpCAM CAR-T cells against the PDOs, which have been found to recapitulate the host tumor genetically and phenotypically." (PMID 41417221, 2025). "An in vitro study revealed that M701 could bridge T lymphocytes to EpCAM-positive tumor cells, which activated T lymphocytes to kill tumor cells." (PMID 41275209, 2025). "While the authors showed that only a small percentage of EpCAM−/CD45− cells had KRAS mutant reads in RNA-seq data, this approach could potentially neglect tumor cell heterogeneity that could account for epithelial PDAC cells that have lost EpCAM expression." (PMID 39584964, 2024). "These antibody-based therapeutics deliver drugs or cytokines directly to the tumor via EpCAM-targeting antibodies, enabling ADCs or immunocytokines to specifically kill tumor cells or activate immune cells within the tumor microenvironment, thereby offering enhanced efficacy and safety." (PMID 39595576, 2024). "However, previous research has shown that EpCAM is overexpressed up to 1000-fold on human tumor tissue compared to healthy tissue, thereby compensating for this potential overestimation." (PMID 37642704, 2024). "As a tumor antigen, EpCAM can be used as an immunotherapeutic target for patients with cancer." (PMID 38187284, 2024). "The EpCAM BiTE molecule effectively formed a binding interaction between EpCAM-positive tumor cells and CD3ε receptors on T cells, subsequently initiating the activation of naive T cells and the subsequent release of various pro-inflammatory factors, including IFN-γ, IL2, IL6, and IL10." (PMID 38464532, 2024). "EPCAM and cytokeratin 19 were reported as progenitor and tumor stem cell markers in HCC." (PMID 38773585, 2024). "The epithelial cell adhesion molecule (EpCAM) was used as a marker for epithelial tumor cells." (PMID 39594628, 2024). "There are few reports on the role of EPCAM in tumour immunity." (PMID 38291183, 2024). "TREX1 was mainly expressed on SCLC tumor cells which are positive for Cytokeratin and EpCAM." (PMID 39177280, 2024). "This required the presence of a second activating αEpCAM–αCD3ε bsAb targeting an abundantly expressed tumor-associated antigen, whereas the mere crosslinking of EpCAM and CD28 by an αEpCAM–αCD28 bsAb was not sufficient." (PMID 39766150, 2024). "Therefore, the differential expression of EpCAM can have an important impact on the biological characteristics of tumor cells, especially the effects of tumor metastasis and recurrence." (PMID 39280341, 2024). "Tumor heterogeneity leads to distinct functions of EpCAM across various tumor types." (PMID 38187284, 2024). "Furthermore, tumor spheroids and EpCAM+ cells were only detected in the bone marrow (BM) of mice with the cisplatin+ and cisplatin++ group, similar to the pattern observed for CTCs." (PMID 39963656, 2024). "Moreover, we observed that the tumor cell marker gene EPCAM exhibited more similar spatial localization with the NECTIN2 than PVR gene in lepidic pattern, which is consistent with the results of scRNA-seq data." (PMID 39474422, 2024).
tumor (continued). "In this study, for the first time, we found that Tregs enhanced the ‘stemness’ of HCC cells, demonstrated by increased TICs ratio, upregulated expression of TICs-related genes CD133, Oct3/4, Sox2, c-Myc, Klf4, Nanog, CD13, EpCAM, elevated tumor sphere formation, and tumorigenic ability." (PMID 39073490, 2024). "To identify the extent of transcriptome remodeling in HCs from tumors (THC), we extracted the tumor fraction and compared the gene expression profile of THC with tumor epithelial cells (EPCAM+ and KRT8+) and THCs with tumor-associated macrophage/monocyte cells (CD14+ and CD163+)." (PMID 38611120, 2024). "Moreover, 1 nM hIMB1636-LDP-AE downregulated the protein levels of stem cell markers that included OCT4, SOX2, EpCAM, and Nanog in all four Trop2+ tumor cell lines." (PMID 38654141, 2024). "In ascites and plasma, EpCAM is present in soluble form (sEpCAM) and on tumor-derived EVs." (PMID 38928484, 2024). "Moreover, EpCAM’s involvement in tumor immune modulation, particularly its ability to resist natural killer cell-mediated cytotoxicity, highlights its significance in tumor immune evasion strategies." (PMID 39033780, 2024). "Furthermore, we observed high levels of factors associated with tumor cell proliferation (CDCP1, EpCAM, EGFR, and PDGFB)." (PMID 38942797, 2024). "These engineered exosomes possess evasion capabilities against phagocytosis, attributed to the abundant CD47 proteins from RBC membranes, alongside specialized tumor-homing properties conferred by cancer cell-derived proteins, including EpCAM, Galectin 3, and N Cadherin." (PMID 38542268, 2024). "Obviously, technical aspects such as different antibodies and staining protocols as well as different scoring criteria have contributed to these differences, making a comprehensive and standardized analysis of EpCAM expression in different human tumor types highly desirable." (PMID 38786342, 2024). "EpCAM expression by tumor cells was confirmed using immunofluorescence staining." (PMID 39358663, 2024). "Higher levels of EpCAM and CEA in tissues are associated with LNM in EAC and could potentially be applied in tumor-target imaging for EAC." (PMID 39399490, 2024). "Our tumor may have an overrepresentation of cells that co-express both EPCAM and CAF transcript markers which might represent epithelial cells transiting to a more “mesenchymal/fibroblast” transcriptomic phenotype." (PMID 39239354, 2024). "To distinguish cancer cells from non-cancerous cells in the organoids and the stromal cell cultures, respectively, we used established tumor marker genes, including PAX8, MUC16 (encoding CA-125) and EPCAM, collectively referred to as PAX8+ cells (Online “Methods”, Suppl." (PMID 39362905, 2024). "Effective tumor-specific labeling was achieved using anti-EpCAM 9C4 and anti-EGFR AY13 mAbs." (PMID 38883274, 2024). "Besides lineage-specific transcription factors, tumor cell clusters shared expression of epithelial marker gene EPCAM and neuron marker gene NCAM1." (PMID 38658971, 2024). "Spatial localization of tumor CD44v6 and EpCAM expression showed distinct expression patterns." (PMID 39356141, 2024). "Furthermore, just one intraperitoneal injection of anti-EpCAM DNA CAR-T cells in mice bearing SKOV3-Luc ovarian tumors resulted in decreased tumor burden and increased survival." (PMID 38612911, 2024). "Furthermore, m801.2 showed strong binding affinity to EpCAM, with KD values of 0.6 nM, and an EpCAM-expressing tumor cell line, comparable to the original IgG m801." (PMID 39595576, 2024). "Furthermore, double immunofluorescence staining showed that the phosphorylation of TBK1 in EpCam+ tumor cells in the combined treatment group was much higher than that in the control group and the monotherapy group." (PMID 39023171, 2024). "When metastatic tumors develop, EpCAM may promote the migration and invasion of tumor cells by inhibiting its expression through some mechanism." (PMID 38187284, 2024).